BRCA2 (BRCA2 DNA repair associated)
Diseases named in the same sentence as BRCA2 in open-access papers (continued):
Sharing a sentence is not in itself a finding about the gene and the disease.
cancer (continued). "Therefore, cancer cells harboring mutated BRCA1 or BRCA2 are particularly sensitive to PARP inhibition." (PMID 37510250, 2023). "At the same time, according to some data from the literature, mutations in the BRCA1 and BRCA2 genes occur in 22–28% of cases; however, these values may vary depending on the type of cancer, ethnic group, and geographic location." (PMID 37628606, 2023). "Pedigree studies based on the UPDB have previously provided the identification of BRCA1 and BRCA2, and more recently have identified additional rare cancer predisposition variants (GOLM1; CELF4; FANCM; ERF; LRBA; FGF5) in similar sets of sampled high-risk pedigrees." (PMID 38136396, 2023). "It is also known that defects in BRCA2 (FANCD1) can lead to cancer predisposition and FA." (PMID 37443752, 2023). "In clinical settings, BRCA1 and BRCA2 are linked to hereditary breast and ovarian malignancies." (PMID 37808268, 2023). "We here show that combining homozygous hypomorphic Brca2/Fancd1 and Rad51c/Fanco mutations in mice by polygenic crosses recapitulates a wide spectrum of the human FA disease, including congenital anomalies, hematopoietic malfunction, and cancer at a young age." (PMID 36906610, 2023). "However, given the limited number of studies focusing on canine BRCA2, it has yet to be proven that BRCA2 mutation is associated with an increased risk of cancer." (PMID 36851449, 2023). "How heterozygous BRCA2 mutations affect epithelial cell lineages, which may predispose these cells towards the development of cancer, remains poorly understood." (PMID 37626143, 2023). "BRCA2 variant carrier cancers are characteristically ER-positive." (PMID 37173335, 2023). "Based on this observation, it is plausible that mutations in ALDH2, a gene coding for aldehyde dehydrogenase to detoxify acetaldehyde, may elevate cancer risk in individuals with a heterozygous BRCA2 truncating mutation such as the BRCA2 p.K3326* mutation." (PMID 37943872, 2023). "The BRCA2 protein plays a crucial role in DNA damage repair, and mutations in the gene can result in increased genomic instability and a higher risk of developing cancer (OMIM #605724, #194070, #1114480, #1612555, #1613029, #155255, #613347, #176807)." (PMID 37623222, 2023). "A large fraction of VUS identified in BRCA1 and BRCA2 are missense changes whose impact on protein function and cancer risk is unknown." (PMID 37168384, 2023). "Based on this observation, we speculate that dysfunctional variants in Aldehyde Dehydrogenase 2 Family Member (ALDH2) may result in aldehyde-induced BRCA2 haploinsufficiency and increase cancer risk in BRCA2 mutation carriers." (PMID 37943872, 2023). "Importantly, the presence of a BRCA2 germline mutation is independently associated with more aggressive cancers and a poorer prognosis." (PMID 38067216, 2023). "In addition, three models predicted BRCA2 monoallelic loss in cancers of the pancreas, breast, and prostate." (PMID 36883553, 2023). "A meta-analysis and systematic review that attempted to compare responses to PARP inhibitors between germline and somatic BRCA1/BRCA2 mutations across cancer types concluded that the drugs appear to be equally effective but noted heterogeneity and possible publication bias." (PMID 36975505, 2023). "Mutations in BRCA1, BRCA2 or PALB2 work synergistically with PARPi to cause cancer cell death." (PMID 37190285, 2023). "Up to 14% of men diagnosed with BC are found to harbor a BRCA2 variant, which is in line with the MBC cases in our population—two in three MBC cases presented a BRCA2 variant, confirming its role as the key gene associated with increased risk of developing this type of cancer." (PMID 37347260, 2023). "The utility of patient-derived missense variants with accompanying clinical data lies not only in their potential to improve cancer risk prediction models but to also provide clinically relevant mutations that can further elucidate the underlying biology of the BRCA2 protein." (PMID 36098506, 2022).
cancer (continued). "BRCA2 PVs were associated with increased risks of male breast (RR = 44.0; 95% CI, 21.3 to 90.9), stomach (RR = 3.69; 95% CI, 2.40 to 5.67), pancreatic (RR = 3.34; 95% CI, 2.21 to 5.06), and prostate (RR = 2.22; 95% CI, 1.63 to 3.03) cancers." (PMID 35077220, 2022). "Therefore, our work provides insights into the origins of cancer in patients carrying BRCA2 mutations." (PMID 36002001, 2022). "Moreover, germline mutations of the BRCA2 gene increase susceptibility to breast, ovarian, pancreatic, and other cancer types, which are more sensitive to radio/chemotherapy." (PMID 35955488, 2022). "Consistent with this role, faults in the DDR (for example those caused by deleterious mutations in DNA repair associated tumour suppressor genes such as BRCA1 and BRCA2) provide the mutagenic fuel that drives oncogenesis and are well described as drivers and hallmarks of cancer." (PMID 35567571, 2022). "Such observed worse outcome may be in keeping with the fact that, among the 22 FANC genes, FANCD2 and FANCD1/BRCA2 are classified as mutated cancer driver genes in CRC according to the IntoGen Compendium." (PMID 35330396, 2022). "Moreover changes in the BRCA1 and BRCA2 genes show an increased risk for the formation of neoplasms of other organs, including cancers of the: prostate, fallopian tube, pancreatic, bladder or melanoma." (PMID 35395863, 2022). "The severity of cancer history for carriers of these variants was also assessed using a history weighting algorithm and was not consistent with pathogenic controls (carriers of known pathogenic variants in BRCA2)." (PMID 33469799, 2022). "Our results indicate that combining functional assay with other forms of data regarding BRCA1 and BRCA2 missense variants can overcome this limitation and lead to a more accurate determination of whether a variant results in increased cancer risk." (PMID 35665744, 2022). "Mutations in BRCA1 and BRCA2, which impair their normal function, have been associated with an elevated risk of breast and ovarian cancer, as well as an increased risk of pancreatic, prostate, stomach, and many other cancers." (PMID 35626055, 2022). "Interestingly, low EZH2 levels correlate with poor survival in patients with BRCA2-mutated cancers, suggesting that EZH2 expression levels, similarly to PTIP, can serve as a biomarker for patient response to PARPi therapy." (PMID 36568963, 2022). "BRCA2 PVs were associated with risks of male breast (RR = 44.0; 95% CI, 21.3 to 90.9), stomach (RR = 3.69; 95% CI, 2.40 to 5.67), pancreatic (RR = 3.34; 95% CI, 2.21 to 5.06), and prostate (RR = 2.22; 95% CI, 1.63 to 3.03) cancers." (PMID 35077220, 2022). "Moreover, the carriers of BRCA2 mutations have a 45-49% risk to develop several types of cancer during their lifes." (PMID 36268271, 2022). "Thus, our work provides a mechanism for how tumor-predisposing BRCA2 inactivation links transcription-induced DNA damage with mitotic DNA repair to fuel the genomic instability characteristic of cancer cells." (PMID 36002001, 2022). "Notably, mutations at the OB-folds domain of BRCA2, which are found from human cancers, abrogated the association with telomere G4, indicating that the failure to associate with telomere G4 is pathogenic." (PMID 35697743, 2022). "In addition to its role in BER, PARP and PAR are important targets in recent and emerging cancer therapies due to the demonstrated synthetic lethality of PARP inhibition in cells with BRCA1/BRCA2 mutations or deletions." (PMID 35954352, 2022). "Inherited cancer predisposition could be related to BRCA1 or BRCA2 mutations in 21.4% of the 524 probands, a proportion that increases to 28.9% of the families with an a priori BRCAPRO mutation probability >10%." (PMID 36230639, 2022). "As it seems unlikely that BRCA2 variants had a protective role against CRCs, these data could indicate a slightly but significantly increased risk of these cancers in men with BRCA1 variants." (PMID 35280729, 2022).
cancer (continued). "Notably, even in BRCA1 and BRCA2 gene mutation carriers, subsequent somatic genetic events must occur to transform a normal cell into a cancer cell that can also result in therapeutic vulnerabilities." (PMID 35703177, 2022). "We searched for both germline and somatic pathogenic variants in BRCA1/2 and BRCAness genes in each of the 33 cancer types and identified a total of 808 germline and 4017 somatic pathogenic mutations in BRCA1, BRCA2 and 37 of the 38 BRCAness genes distributed in 33 cancer types." (PMID 36497135, 2022). "However, only the minority of cancers have BRCA1 or BRCA2 mutations that would confer sensitivity to PARP inhibitors (PARPi)." (PMID 35869047, 2022). "This approach is validated by the observation that known SMYD3 interactors, such as VGFR1, which is involved in cancer hallmark “inducing angiogenesis”, and ATM and BRCA2, which are involved in cancer hallmark “genome instability & mutation”, show a significant enrichment in P-tripeptides." (PMID 35495117, 2022). "Most of the therapeutic strategies using PARP inhibitors rely on their blockade of DDR and the creation of synthetic lethality in combination with genetic defects in homologous recombination-mediated repair, which are the basis for the treatment of patients with BRCA1- and BRCA2-associated cancers." (PMID 35545049, 2022). "In other words, a BRCA2-mutated cancer cell at the primary site (prostate) may express high PSA while a cell with same genetic background but located in bone marrow may express less PSA." (PMID 36362213, 2022). "For instance, PARP inhibitors have been used for cancer patients with BRCA1/BRCA2 mutation." (PMID 36212008, 2022). "The co-localization of MiDAS sites identified in BRCA2-deficient cells with R-loops and their dependence on TRCs led us to investigate whether these sites are prone to chromosome rearrangements in cancers." (PMID 36002001, 2022). "Prior studies also support the idea that the C-terminal antibody could be useful in screening cancers for BRCA mutations as well as BRCA2 protein expression in patients with unknown mutation status." (PMID 36230652, 2022). "A PARP inhibitor olaparib has been approved as a therapeutic agent for cancer patients with BRCA1 or BRCA2 mutations, although its effects on metabolic bone diseases and bone formation remain unclear." (PMID 35563432, 2022). "Multiple studies have found poor survival for BRCA2 carriers compared with noncarriers–72BRCA2 carriers have a stronger association with Gleason score ≥ 7 cancer than with Gleason score ≤ 6, cancer and a higher risk of death from prostate cancer." (PMID 35732815, 2022). "Thus, BRCA1- or BRCA2-mutated cancer cells exhibit an increased sensitivity to PARP inhibitors when compared to normal cells." (PMID 35328658, 2022). "Furthermore, inhibiting RAD52 in cancer cells harboring BRCA2 mutations can selectively and effectively kill cells." (PMID 36107942, 2022). "Moreover, Friebel shows in a systematic review that the cancer risk of women who have inherited a BRCA1 or BRCA2 (BRCA1/2) mutation is highly variable." (PMID 35885460, 2022). "Conferred cancer risks differ for pathogenic variants in BRCA1 or BRCA2 genes." (PMID 36358902, 2022). "Although BRCA1 and BRCA2 are ubiquitously expressed in cells of the human body, pathogenic germline mutations in these genes confer significantly elevated risk of developing various cancers, notably, cancers of the breast and ovary." (PMID 35668475, 2022). "The discovery of BRCA1 and BRCA2 gene pathogenic variants has made it possible to identify high oncologic risk populations and improve their life expectancy with individualized screenings, early cancer diagnosis, novel therapies and prophylactic procedures." (PMID 36497251, 2022). "The contribution of germline copy number variants (CNVs) to risk of developing cancer in individuals with pathogenic BRCA1 or BRCA2 variants remains relatively unknown." (PMID 36203093, 2022).
cancer (continued). "BRCA1 and BRCA2 are the two most well-known cancer predisposition genes." (PMID 35625955, 2022). "The term “genetic responsibility” has been coined in the medical sociology literature, and could be applied to the present study, but has primarily been explored in the context of genetic screening for cancer-associated genes such as BRCA1/BRCA2." (PMID 34831944, 2021). "Two large pan-cancer trials suggest that checkpoint inhibitors might be more effective in BRCA2-mutated tumors, but this requires further validation." (PMID 34067105, 2021). "Furthermore, we propose a straightforward methodology that produces conclusive results in a reasonable turnaround time to classify BRCA2 variants of uncertain significance (VUS) in cancer patients." (PMID 34504103, 2021). "However, the benefit of prophylaxis mastectomy has only been proven in some specific genetic-related cancer types, such as BRCA1 and BRCA2, in reducing contralateral cancer risk; the benefit for survival remains under debate." (PMID 34209279, 2021). "The major reason behind this association might be inherited gene mutation such as Breast Cancer Gene 1 (BRCA1) or Breast Cancer Gene 2 (BRCA2) mutations." (PMID 33446123, 2021). "The aggressive behavior of these cancers may be further promoted by concomitant BRCA1 or BRCA2 mutations, cooperating with Notch signaling towards cancer progression." (PMID 33430387, 2021). "Finally, family members responded differently to familial predisposition to cancer: Fact-oriented reactions concerning the familial BRCA1 or BRCA2 mutation were observed in individuals with an own history of cancer." (PMID 34635688, 2021). "Further research is required to determine their efficacy in the delay or prevention of cancer onset in the carriers of germline BRCA1/BRCA2 variants, as well as to investigate their potential toxicity, risk of secondary cancer development and any mechanisms of resistance." (PMID 34771713, 2021). "The BRCA2 999del5-associated cancer risk is most probably due to haploinsufficiency." (PMID 34830851, 2021). "Secondary intragenic mutations in BRCA2 may be one reason for acquired drug resistance in BRCA2-mutated cancers." (PMID 33868274, 2021). "BRCA2 c.5164_5165delAG was a known pathogenic variant in Chinese cancer patients." (PMID 34235180, 2021). "The possibility also exists that BRCA2 may have multiple functions associated with cancer risk, although evidence to date shows that all pathogenic missense variants influence HDR activity." (PMID 33609447, 2021). "Although BRCA1- or BRCA2-deficient cancer cells exhibiting defects in homologous recombination (HR deficiency) are hypersensitive to PARP inhibitors through the mechanism of synthetic lethality, acquired resistance to PARP inhibitors was observed in patients with HR deficient HGSOC." (PMID 34063568, 2021). "However, in cancer cells deficient for BRCA1/BRCA2, the lesions resulting from PARP trapping cause irreversible damage that kills the cells." (PMID 34950659, 2021). "A defect in BRCA2 HR function causes genetic instability and increases cancer risk." (PMID 34356684, 2021). "Identifying carriers of BRCA1 and BRCA2 pathogenic variants for cancer prevention (prophylactic surgery) and management of OC using new therapies (e.g. poly (ADP-ribose) polymerase inhibitors (PARPi)) is being offered in medical genetic and gynecologic oncology settings." (PMID 34861889, 2021). "Similarly, such strategy can be used to measure the impact of a cancer-associated mutation on the solution structure of a BRCA2 IDR." (PMID 34356684, 2021). "In this study, we have performed a virtual screening by targeting the self-association domain (residues 85–159) of RAD52 with a library of 66,608 compounds and found one compound, C791-0064, that specifically inhibited the proliferation of BRCA2-deficient cancer cells." (PMID 33995041, 2021).
cancer (continued). "Similarly to BRCA1 or BRCA2 gene mutations, oncogene activation represents an early driver of tumourigenesis, providing cancer cells with selective growth advantage." (PMID 34389725, 2021). "Cancer-associated mutations in BRCA2 are commonly found in the BRC repeat and OB-fold regions." (PMID 34065235, 2021). "Thus, individuals who carry BRCA2 mutations have elevated risks for breast, ovarian, prostate, pancreatic, and other cancers." (PMID 34440403, 2021). "FA might be implicated in cancer development in patients carrying mutations in the tumour suppressor BRCA2, and in the onset of some human conditions such as Fanconi Anaemia." (PMID 33495466, 2021). "BRCA2 heterozygosity is associated with a cancer susceptibility phenotype." (PMID 34359565, 2021). "As morbidity increases, it has been recognized that genetic factors are associated with early-onset breast cancers, such as hereditary breast cancer and ovarian cancers, in which breast cancer susceptibility gene I (BRCA1) and breast cancer susceptibility gene II (BRCA2) play a role." (PMID 33492646, 2021). "To address whether these cancer mutations impact on the function of BRCA2, we investigated the cell viability and DNA damage tolerance of cells expressing BRCA2 S1106R, T1116P, and T1128I in our RNAi and complementation system in U2OS Flp-In T-REx cells." (PMID 34593815, 2021). "In other studies, BRCA2 c.9976A>T carrier status was associated with a moderate risk for cancer." (PMID 33672545, 2021). "Moreover, we find that several cancer-associated mutations in BRCA2 deregulate the BRCA2-PP2A-B56 interaction and sensitize cells to PARP inhibition." (PMID 34593815, 2021). "Thus, our results suggest that even a small reduction in DSS1 binding significantly impairs the nuclear localization of cancer-causing BRCA2 mutants within the DSS1-binding region of the DBD." (PMID 33978741, 2021). "Thus, our results provide a rationale for targeting BRCA2 deficiencies in human cancers by pharmacological inactivation of DNA repair/replication stress response helicases implicated in fork stability maintenance." (PMID 34772932, 2021). "Thus, our studies suggest that the disruption of DSS1-regulated BRCA2 assembly and nuclear transport underlies the pathogenicity of cancer-causing mutations affecting the DBD." (PMID 33978741, 2021). "Thus, our work opens opportunities for cancer prevention in patients who carry particular BRCA2 missense mutations." (PMID 33978741, 2021). "We recently showed that S206C and T207A lead to chromosomal instability including aneuploidy as observed in BRCA2 mutated tumors, which we proposed could have an impact on cancer." (PMID 34356684, 2021). "Thus, our results agree with previous reports on distinctive mechanisms associated with the dysfunction of BRCA1 or BRCA2 in cancers." (PMID 33525353, 2021). "However, BRCA2-deficient cancer cells can survive in virtue of high tolerance of endogenous DNA damage." (PMID 33791310, 2021). "Indeed, the initial designation of these compounds to BRCA1/BRCA2-mutated cancers already stemmed from the discovery of the synthetic lethal relationship between PARP1/PARP2 inhibition and faulty HR machinery." (PMID 34210965, 2021). "Studies have shown that mammography adds only a small amount of cancer detection to BRCA1 mutation carriers under 40 years old if screening with MRI regularly, while BRCA2 mutation carriers benefit from mammography and MRI, because more cancers are found only through mammography." (PMID 33932123, 2021). "BRCA1 and BRCA2 have been established as high risk cancer predisposing genes, as heterozygous carriers of pathogenic variants (PVs; all variants in this review are germline unless otherwise stated) have absolute risks greater than 60% for BC and 13–58% for OC, depending on the gene involved." (PMID 34298626, 2021). "C791-0064 could serve as a promising leading compound in future studies for targeted cancer therapy in the context of BRCA2 deficiency." (PMID 33995041, 2021).